KRAS (KRas proto-oncogene, GTPase)
Diseases named in the same sentence as KRAS in open-access papers (continued):
Sharing a sentence is not in itself a finding about the gene and the disease.
lung cancer (continued). "We chose 2 blood cancer cell lines (Jurkat and HL60, wild-type KRAS), 2 lung cancer cell lines (NCI-H661 and NCI-H1703, wild-type KRAS), and 2 pancreatic cancer cell lines (YAPC and SW1990, mutant KRAS) for these studies." (PMID 34257283, 2021). "Effective therapies have been currently developed to target EGFR, KRAS, and MET; however, the prognosis of patients with advanced lung cancer remains unsatisfactory." (PMID 33981850, 2021). "Whereas both MAPK and PI3K are well known major effector pathways of KRAS, PI3K was shown to be dominantly regulated by RTKs, chiefly IGFR in colorectal and lung cancer." (PMID 34680229, 2021). "In lung cancer, STAT3 was shown to play an unexpected tumor-suppressive role in KRAS-mutant lung adenocarcinoma." (PMID 34679602, 2021). "Instead, SOD1 is crucial for sustaining the growth of lung cancer cells in KRAS-driven lung tumors in a GEM model as well as cultured human and mouse lung cancer cells." (PMID 33859191, 2021). "HER2 mutations mainly occur at exon 20 in the protein kinase domain and are recognized as primary drivers in lung cancer, similar to other oncogenic drivers, such as EGFR, ROS, ALK, KRAS and BRAF." (PMID 33959501, 2021). "Three cell lines, including H1299 (lung cancer), A549 (lung cancer), and T24 (bladder cancer), harboring the NRAS, KRAS, and HRAS oncogene, resp., were transfected with the PY4- -Luciferase and Ranila plasmids." (PMID 34172933, 2021). "Small molecular inhibitors, effecting on KRAS, EGFR, ALK in lung cancer 11, BRAF and MEK in melanoma cells 63, elicit concurrent GSDME-mediated PCD." (PMID 34335940, 2021). "However, the function of SDPR in lung cancer, especially in KRAS-mutant group, remains unclear." (PMID 33435990, 2021). "YAP/TAZ also participates in KRAS oncogene-driven pancreatic ductal carcinoma, and KRAS and YAP signaling pathways converge to regulate the epithelia-mesenchymal transition in lung cancer." (PMID 34073318, 2021). "Here, we identify and characterize a KRAS-responsive lncRNA, KIMAT1 (ENSG00000228709) and show that it correlates with KRAS levels both in cell lines and in lung cancer specimens." (PMID 33795683, 2021). "The GSE72526 was a dataset using microRNA to predict ALK, EGFR, and KRAS statuses in lung cancer patients and to use ALK, EGFR, and KRAS as biomarkers to diagnose lung cancer." (PMID 31976313, 2020). "Aberrant changes in KRAS, EGFR, ALK have been recognized as key drivers of lung cancer, and are frequently identified in LUAD." (PMID 32855362, 2020). "In lung cancer, IL-6/STAT3 signalling induced by KRAS oncogene has contrasting roles in its initiation and progression." (PMID 33116132, 2020). "These authors demonstrated that using the dual AURKA and AURKB inhibitor, AI II, reduces growth, viability, and anchorage-independent growth in a KRAS-dependent manner, showing that AURKA and AURKB are promising targets for KRAS-induced lung cancer therapy." (PMID 33202573, 2020). "Among identified pathways, we highlight the EGFR, FGFR1, KRAS, and PI3K-AKT signaling, and other well-known lung cancer pathways, such as MAPK and mTOR." (PMID 32726984, 2020). "Among those tested, the most common tests administered during baseline were EGFR, molecular cytogenetics (FISH) for ALK or ROS-1, tumor immunochemistry panels (PD-1, PD-L1) and combination lung cancer panels (EGFR, KRAS, ALK, ROS-1, and PD-L1)." (PMID 32187231, 2020). "Here we show that genetic inhibition of SHOC2 suppresses tumorigenic growth in a subset of KRAS-mutant NSCLC cell lines and prominently inhibits tumour development in autochthonous murine KRAS-driven lung cancer models." (PMID 31182717, 2019).
lung cancer (continued). "Lung cancer was the most commonly reported neoplasm, and EGFR, KRAS, and ALK analysis using polymerase chain reaction or fluorescence in situ hybridization was achieved in 67%–100% of the specimens." (PMID 31179853, 2019). "Kim and colleagues tested 230,000 synthetic small molecules in a panel of 91 lung cancer-derived cell lines, identifying coatomer complex I (COPI) as necessary for the survival of LKB1/KRAS double mutant NSCLC." (PMID 31781355, 2019). "In the context of lung cancer, it will be of interest to assess the driver role of ADAM17 in other lung cancer subtypes (e.g., KRAS wild-type LAC, EGFR mutant LAC, squamous cell carcinoma)." (PMID 31438559, 2019). "In two recent studies of lung cancer cells, the pro-metastatic basic leucine zipper transcription factor 1 (BACH1) has been found to promote metastasis in KRAS-driven tumor cells." (PMID 31434226, 2019). "The distinct molecular subtypes of lung cancer are defined by monogenic biomarkers, such as EGFR, KRAS, and ALK rearrangement." (PMID 31480292, 2019). "KRAS, which is another activator of the Ras/Raf/MEK/ERK pathway, is repressed by the let-7 family, slowing the in vitro growth of lung cancer cells." (PMID 31818027, 2019). "In addition, previous studies have indicated that KRAS mutations are associated with worse survival, and these mutations are thought to be a negative prognostic marker in patients with lung cancer, especially patients with adenocarcinoma and early stage disease." (PMID 31783917, 2019). "In transgenic mouse models of lung cancer, Dusp6 RNA was present at significantly higher levels in the lungs of mice bearing tumors driven by mutant EGFR or KRAS transgenes than in normal mouse lung epithelium." (PMID 30475204, 2018). "YAP overexpression in the KRASG12D lung cancer mouse model accelerates lung adenocarcinoma progression; conversely, YAP deletion markedly delayed tumor progression in KRAS-mutant mice." (PMID 30060526, 2018). "For example, studies of mouse models of Kirsten rat sarcoma viral oncogene homolog (KRAS; G12D)-induced lung cancer have demonstrated that KRAS activates NF-κB in lung tumours in situ." (PMID 30142927, 2018). "In the multivariable analysis, only lung cancer as well as the presence of ARID1A, KRAS, ALK, and MYC alterations and liver metastasis remained significant predictors of a poorer survival (all P < 0.50)." (PMID 29866143, 2018). "For example, in lung cancer, a germline SNP in the 3′UTR of KRAS proto-oncogene abrogated the binding site of let-7, thus increasing KRAS protein levels and promoted tumor progression." (PMID 30018188, 2018). "In the case of lung cancer, it is well known that EGFR or KRAS affects the AKT pathway, whereas wild-type EGFR was reported to be associated with B7-H3 expression." (PMID 30513627, 2018). "These HKGs have low expression variation compared to current lung cancer markers (e.g., EGFR, KRAS) and were involved in the most common biological processes (e.g., metabolism, stress response)." (PMID 29761043, 2018). "Loss of KEAP1, a negative regulator of NFE2L2/NRF2, modulated the response to BRAF, MEK, EGFR, and ALK inhibition in BRAF-, NRAS-, KRAS-, EGFR-, and ALK-mutant lung cancer cells." (PMID 28145866, 2017). "He talked about RAS mutations and their centrality to lung cancer, introducing the KRAS LA2 and KRAS LSL mouse models that are able to replicate the initiation and progression of human lung cancer in vivo." (PMID 28386299, 2017).
lung cancer (continued). "Because KRAS is an effector of EGFR, the EGFR-RAS-RAF-MEK-ERK cascade is considered a target-rich environment for medical management of lung cancer." (PMID 29088821, 2017). "Fortunately, over past decades, the finding of some driver genes in NSCLC, such as epidermal growth factor receptor (EGFR), anaplastic lymphoma kinase (ALK) and kirsten rat sarcoma viral oncogene homolog (KRAS), was a major breakthrough in lung cancer field." (PMID 28423587, 2017). "For gain-of-function of KRAS, we used HA-tagged KRASG12V-inducible H1703 human lung cancer cells, that express oncogenic KRASG12V upon doxycycline administration." (PMID 26842935, 2016). "When they further examined a set of lung cancer cell lines with mutant or wild-type KRAS, treatment with the MEK/PI3K/HDAC inhibitor combination elicited apoptosis only in the KRAS mutant cell lines." (PMID 27634878, 2016). "Molecular alterations in EGFR, KRAS, and ALK genes are involved in lung cancer pathogenesis, but clinical use of these biomarkers is still a debatable issue." (PMID 27863408, 2016). "Previous studies identified three major genes (EGFR, KRAS, and ALK) for the development of lung cancer." (PMID 27863408, 2016). "Other synthetic lethal partners that have been identified through RNAi screening within an activated KRAS background include STK33, TBK1, WT1, CDK1, CDK4, GATA2, and Snail2, studies conducted primarily using colon and lung cancer cells." (PMID 27686855, 2016). "Our data proved that RMRP acted as an oncogene LncRNA to promote the expression of KRAS, FMNL2 and SOX9 by inhibiting miR-206 expression in lung cancer." (PMID 27906963, 2016). "In addition to the PIK3CA mutant tumor cells as we tested in this study, we and others also observed that in KRAS mutant and wild-type colon and lung cancer cells, rapamycin could also elicit AKT activation and increase the level of AKT-mediated phosphorylation of PRAS40 on Thr246." (PMID 25961827, 2015). "An interesting feature of the let-7 family is that the 3′-UTR of KRAS (as well as HRAS, NRAS, and various members of the RAS GTPase family) contain multiple let-7 binding sites, and let-7 levels in lung cancer inversely correlate with KRAS expression." (PMID 26583084, 2015). "NKX2-1 likely plays distinct roles in the context of EGFR-driven and KRAS-driven lung cancers, with Egfr-driven murine tumors perhaps more closely modeling NKX2-1 amplified human lung cancer." (PMID 26556242, 2015). "For lung cancer, factors, such as age, gender, stage, smoking history, Myc protein level, and EGFR/KRAS/ALK alteration status were included in the multivariate model." (PMID 25333947, 2014). "In the Lung1 cohort, when grouped by age, EGFR/KRAS/ALK alteration status, and smoking history, N39 further stratified lung cancer patients with significant differences in survival." (PMID 25146220, 2014). "In nonsmall-cell lung cancer (NSCLC), one of the most commonly genetic aberrations is conversion of the protooncogene KRAS to its activated oncogenic form." (PMID 24729895, 2014). "In order to further assess this dependency, we used H1703 lung adenocarcinoma cells, which harbor wild-type KRAS, to generate HA-tagged KRASG12V-inducible H1703 human lung cancer cells." (PMID 24955217, 2014). "Importantly, regardless of whether there is an exclusive association between KRAS mutation and TWIST1 overexpression in human lung cancer cells, the data presented strongly support that TWIST1 upregulation in KRAS mutant lung cancer represents a novel and particularly promising therapeutic target." (PMID 22654667, 2012). "Most of these mutations were frequently observed in certain focused pathways, e.g., four genes from the EGFR-RAS-RAF signaling pathway, EGFR, KRAS, HER2, and BRAF, behave in a mutual exclusive fashion in lung cancer." (PMID 22624051, 2012).
lung cancer (continued). "We have previously reported that mutations of EGFR, KRAS, BRAF and HER2 were mutually exclusive in 691 resected NSCLC tumors indicating that a single activating mutation in the EGFR-RAS-RAF signaling pathway may be sufficient for the pathogenesis of many lung cancers." (PMID 19238210, 2009). "Interestingly, KRAS mutations may also predict lack of response to EGFR tyrosine kinase inhibitors (TKI) in lung cancer, suggesting a common mechanism of resistance to anti-EGFR therapies in these two tumor types." (PMID 19439077, 2009). "Together, these results indicate that PIK3CA is not required for lung cancer cell growth induced by mutant KRAS in vitro but is essential for in vivo progression and growth." (PMID 41892297, 2026). "Together, these results demonstrate that PIK3CA is not required for lung cancer cell growth induced by mutant KRAS in vitro but is critically needed for in vivo progression and growth." (PMID 41676515, 2026). "At the molecular level, lung cancers in non-smokers often harbor specific genetic mutations such as those in the EGFR gene, KRAS mutations, and ALK rearrangements." (PMID 40821300, 2025). "For example, heightened intronic hypermethylation in the KRAS gene may continuously activate the MAPK signaling pathway, facilitating lung cancer cell proliferation via enhancer hijacking." (PMID 40725119, 2025). "KRAS was historically considered an “undruggable” target until the advent of the selective KRAS G12C inhibitor sotorasib (AMG-510), which offered new hope for lung cancer treatment." (PMID 41463025, 2025). "In the context of epigenetic initiation, different histological types of lung cancer each exhibit distinct genomic characteristics, such as RB1 and MYC alterations in SCLC, NFE2L2, TP63 and NOTCH1 variations in LUSC, and EGFR, KRAS and ERBB2 variations in LUAD." (PMID 40847555, 2025). "Known lung cancer genes (EGFR, KRAS G12C, ALK, MET, RET) were found in 33 patients; 11 had genes relevant to both lung and other cancers (ERBB2, BRAF V600, NTRK), and 37 had genes typically linked to other malignancies (NF1, PIK3CA, PALB2, FGFR2B, FBX7, RAD51)." (PMID 40244261, 2025). "Although HER2 mutations are not as common as other mutations like EGFR or KRAS in lung cancer, the discovery of effective therapies targeting HER2 mutations has been a breakthrough in lung cancer treatment." (PMID 41180730, 2025). "Although specific somatic mutations—such as those in EGFR, KRAS, and EML4-ALK—have been identified, particularly in lung adenocarcinoma, they are absent in the majority of patients with lung cancer." (PMID 41241099, 2025). "In contrast, lung cancers exhibit prognostic variations based on the presence of EGFR and KRAS, influenced in part due to historic availability of highly active EGFR tyrosine kinase inhibitors; in the breast, presence or absence of estrogen receptor expression dictates therapeutic options." (PMID 40647516, 2025). "In the context of lung cancer, circulating tumor DNA (ctDNA)-based assays enable the identification of clinically targetable mutations, such as EGFR, ALK, and KRAS, without the need for a tissue biopsy." (PMID 41303058, 2025). "Very recently, the KRASG12C inhibitor sotorasib and the MAP2K4 inhibitor HRX-0233 were shown to synergistically inhibit growth of a number KRAS mutant CRC and lung cancer cell lines and to induce durable tumor shrinkage in mouse xenografts of human lung cancer cells." (PMID 40419504, 2025).
lung cancer (continued). "The introduction of specific KRAS G12C inhibitors to the clinical practice in lung cancer has opened up opportunities that did not exist before." (PMID 38639476, 2024). "The reproducible resistance mechanism observed in MIA PaCa-2 cells was distinct from KRAS-mutant colon and lung cancer models, which evidenced neither ABCG2 upregulation nor resensitization to ERK inhibition by pharmacologic ABCG2 inhibition." (PMID 38822082, 2024). "In AKT1 (r = −0.15, p < 0.05), BRAF (r = −0.25, p < 0.05), GAPDH (r = −0.3, p < 0.05), KRAS (r = −0.24, p < 0.05), MYC (r = −0.25, p < 0.05), and SRC (r = −0.24, p < 0.05), stromal score was negatively correlated with lung cancer and the highest correlation coefficient was in GAPDH." (PMID 39734333, 2024). "Furthermore, the interaction between CPH with prominent lung cancer pathways such as KRAS and EGFR and their inhibitors should be further evaluated in lung cancer cell lines that show different sensitivity to KRAS inhibitors." (PMID 39522095, 2024). "Notably, our study identified a negative correlation between the expression of key hub genes (AKT, BRAF, GAPDH, KRAS, MYC, and SRC) and immune and stromal cell content in the lung cancer TME." (PMID 39734333, 2024). "Here, we present a 10XGenomics scRNA-seq experiment, providing a controlled heterogeneous environment using lung cancer cell lines characterised by the expression of seven different driver genes (EGFR, ALK, MET, ERBB2, KRAS, BRAF, ROS1), leading to partially overlapping functional pathways." (PMID 38307867, 2024). "EGCG selectively inhibited the growth of KRAS-mutant lung cancer cells without affecting KRAS wild-type cells." (PMID 39725830, 2024). "This sensitivity was also observed in lung cancer cell lines with LKB1 and KRAS co-mutations, but the single mutation did not confer it." (PMID 39544365, 2024). "It has since been indicated that concomitant inhibition of SOS1 can improve sensitivity to MEK inhibition in a G12 and G13 mutant KRAS context, but this is not seen in KRAS-Q61 mutant cases of lung cancer." (PMID 39372214, 2024). "Here, we discover that lactate dehydrogenase (LDH) B, but not the closely related LDHA, subunits of active LDH with a known function in glycolysis, noncanonically promotes ferroptosis defense in KRAS-driven lung cancer." (PMID 39643712, 2024). "It has been shown that the Pdk1 effector from the PI3K pathway is essential for KRAS G12D-driven PDAC but not for G12D-driven lung cancer." (PMID 39457426, 2024). "In this case, the NRAS mutation was predominantly identified, the most common gene mutations in lung cancer are all negative, including EGFR, KRAS, BRAF, ALK, ROS1, and so on." (PMID 39507527, 2024). "Intriguingly, a previous study demonstrated that KL lung cancer model had high levels of collagen deposition compared to KRAS-only model, while the mechanistic explanation was not clearly illustrated." (PMID 38291516, 2024). "The findings of an electronic search for publications using RET-FISH in lung cancer were compared with the results obtained at the Grenoble University Hospital where 784 EGFR-, KRAS-, ALK-, and ROS1-negative NSCLCs were tested by RET break-apart FISH and confirmed by RNA-sequencing (RNA-seq)." (PMID 39507413, 2024). "We also explored the clinical significance of HOXC10 expression in different KRAS-mutant lung cancer patients with/without bone metastasis." (PMID 39191757, 2024).